WTAP (WT1 associated protein)
Diseases named in the same sentence as WTAP in open-access papers (continued):
Sharing a sentence is not in itself a finding about the gene and the disease.
osteosarcoma (13 papers, 2020 to 2025). A usually aggressive malignant bone-forming mesenchymal neoplasm, predominantly affecting adolescents and young adults. "For instance, WTAP, which is highly expressed in osteosarcoma tissues and linked with the worse prognosis of osteosarcoma patients, was found to potentially promote osteosarcoma progression by inhibiting HMBOX1 in an m6A-dependent manner in vitro and in vivo." (PMID 34733885, 2021). "Here, we revealed the increased expression of WTAP in osteosarcoma tissue, which was associated with clinicopathological features and poor prognosis in osteosarcoma patients." (PMID 32814762, 2020). "In this study, WTAP was firstly identified to upregulated which was associated with poor prognosis of osteosarcoma." (PMID 32814762, 2020). "For instance, WTAP, which is highly expressed in osteosarcoma tissues and associated with the worse prognosis of osteosarcoma patients, was found to potentially promote osteosarcoma progression by inhibiting HMBOX1 in an m6A-dependent manner in vitro and in vivo." (PMID 36313417, 2022). "The HMBOX1 is involved in the proliferation and metastasis of osteosarcoma, which is mediated by WTAP in vitro." (PMID 37915034, 2023). "LncRNA SNHG10 competes for binding miR-141-3p by acting as a ceRNA to upregulate WTAP expression in osteosarcoma." (PMID 36139062, 2022). "WTAP is highly expressed in osteosarcoma tissue and regulats the proliferation and metastasis of osteosarcoma by PI3K/AKT pathway." (PMID 35735243, 2022). "WTAP was found to be highly expressed in osteosarcoma, and it was a significant independent prognostic factor for overall survival." (PMID 36207306, 2022). "Mechanistically, lncRNA SNHG10 competes as ceRNA to bind miR-141-3p and upregulates WTAP expression to maintain the malignant features of osteosarcoma." (PMID 36139062, 2022). "WTAP function as an oncogenic gene and it promotes the m6A modification and progression of osteosarcoma." (PMID 32814762, 2020). "In this study, WTAP was found to be highly expressed in osteosarcoma tissue and it was an independent prognostic factor for overall survival in osteosarcoma." (PMID 32814762, 2020). "Collectively, these results demonstrated that WTAP is highly expressed in osteosarcoma and is correlated with its poor prognosis." (PMID 32814762, 2020). "Functionally, WTAP, as an oncogene, was involved in the proliferation and metastasis of osteosarcoma in vitro and vivo." (PMID 32814762, 2020). "And the univariate and multivariate cox analysis showed that WTAP and metastasis were the independent prognostic factor for overall survival in osteosarcoma patients." (PMID 32814762, 2020). "In conclusion, these results indicated that HMBOX1 is a potential target of WTAP and is related to poor prognosis of osteosarcoma patients." (PMID 32814762, 2020). "Functionally, WTAP promoted the growth and metastasis of osteosarcoma in vitro and vivo." (PMID 32814762, 2020). "WTAP/HMBOX1 regulated osteosarcoma growth and metastasis via PI3K/AKT pathway." (PMID 32814762, 2020). "Finally, WTAP/HMBOX1 regulated osteosarcoma growth and metastasis via PI3K/AKT pathway." (PMID 32814762, 2020). "Finally, we analyzed the downstream pathway of WTAP/HMBOX1 in osteosarcoma." (PMID 32814762, 2020). "Finally, WTAP/HMBOX1 regulated osteosarcoma growth and metastasis in a PI3K/AKT-dependent pattern." (PMID 32814762, 2020). "Nevertheless, current research on m6A methylation modifications in osteosarcoma has predominantly focused on METTL3, METTL14, WTAP, ALKBH5, and YTHDF2, with few studies on other m6A methylation regulators." (PMID 40176793, 2025). "WTAP and HMBOX1 modulate the PI3K/AKT pathway to regulate the growth and metastasis of osteosarcoma." (PMID 37915034, 2023). "In osteosarcoma, low HMBOX1 expression predicts poor overall survival and is involved in WTAP-mediated proliferation and metastasis of osteosarcoma." (PMID 36139062, 2022).
osteosarcoma (continued). "We found that in osteosarcoma samples with metastasis, METTL14 exhibited significantly decreased expression, and WTAP were significantly differentially expressed." (PMID 34011074, 2021). "Moreover, there was a significant decrease in demethylase ALKBH5 mRNA inversely correlated with m6A contents in all three osteosarcoma cell lines as compared with hOB cells, but not in METTL3, METTL14, WTAP, and FTO." (PMID 33431791, 2021).
ovarian carcinoma (13 papers, 2019 to 2024). A malignant neoplasm originating from the surface ovarian epithelium. "β-arrestin 2 can also promote colorectal cancer growth and migration, and proliferation and anti-apoptosis of ovarian cancer cells by triggering Wilms tumor 1-associated protein (WTAP)." (PMID 36010884, 2022). "In this study, we evaluated the effects of 18 regulators of m6A modification on the prognosis of ovarian cancer and found that high expression of WTAP was a risk factor for the prognosis of ovarian cancer." (PMID 32998774, 2020). "CDH2, ALKBH5, ELAVL1, and WTAP are the key regulators that exert a critical impact on the development and prognosis of ovarian cancer." (PMID 37684273, 2023). "Subsequently, we used the ssGSEA algorithm and overall survival analyses to identify the key prognosis-related immunological signatures in ovarian cancer, which included WTAP, ELAVL1, CDH2, and ALKBH5." (PMID 37684273, 2023). "In our current study, according to the Kaplan–Meier plotter database, when YTHDF1, YTHDF2, WTAP, FTP, and ALKBH5 were highly expressed in ovarian cancer, they were validated as valuable prognostic risk factors for low OS and PFS with high HR." (PMID 33225598, 2021). "In this study, we found that WTAP functions as an oncogenic factor that promotes the progression of ovarian cancer." (PMID 32998774, 2020). "Functionally, WTAP promoted the proliferation, invasion, and migration capability of ovarian cancer, according to the results of real time cellular analysis (RTCA), EdU cell proliferation assay, transwell assay." (PMID 32998774, 2020). "Our study indicates the potential role of WTAP in prognostic biomarker and therapeutic target for ovarian cancer." (PMID 32998774, 2020). "Levels of the m6A methylase “writers,” including METTL3, METTL14 and WTAP, were increased in brain, central nervous system (CNS), cervical, and head and neck cancer and sarcoma but decreased in BC, lymphoma and ovarian cancer as compared with normal controls." (PMID 30953473, 2019). "Knockdown of WTAP in ovarian cancer cells decreased expression of several MAPK proteins such as p-ERK, ERK, p-JNK, JNK, p38 and p-p38 as well as AKT pathway proteins (p-AKT, AKT) indicating the association of these two pathways with WTAP in ovarian cancer." (PMID 33814008, 2021). "WTAP functions as an oncogenic factor that promotes the progression of ovarian cancer in which WTAP-HBS1L/FAM76A axis may be involved." (PMID 32998774, 2020). "This study identified four-DERRG signature (ALYREF, ZC3H13, WTAP, and METTL1) in OC, which was an independent prognostic model for patient stratification, prognostic evaluation, and prediction of response to immunotherapy in ovarian cancer by classifying OC patients into high- and low-risk groups." (PMID 36545327, 2022). "It was intriguing whether WTAP also contributes to cancer progression and affects the expression of tumour-related genes through transcriptional or post-transcriptional regulation of mRNA in ovarian cancer." (PMID 32998774, 2020). "WTAP may be a promising prognostic biomarker and therapeutic target for ovarian cancer." (PMID 32998774, 2020). "Next, utilizing the ssGSEA algorithm and conducting overall survival analyses, we have identified the key prognosis-related immunological signatures in ovarian cancer to be ALKBH5, WTAP, ELAVL1, and CDH2 as the regulators." (PMID 37684273, 2023). "Simultaneously, to understand the biology behind the key signatures, the protein expression of ALKBH5, WTAP, ELAVL1, and CDH2 in ovarian cancer was analyzed using CPTAC datasets." (PMID 37684273, 2023). "Additionally, significant correlations were observed between the methylation of ALKBH5, WTAP, ELAVL1, CDH2 and immunoinhibitors, immunostimulators, and MHC molecules in ovarian cancer using Spearman’s correlation analysis." (PMID 37684273, 2023). "Except WTAP, the role of both HNRNPA2B1 and KIAA1429 in ovarian cancer has not been thoroughly studied and can be used to direct further research." (PMID 34187307, 2021).
pancreatic cancer (13 papers, 2020 to 2025). "A multivariate Cox regression analysis indicated that nuclear WTAP expression was an independent prognostic indicator for pancreatic ductal adenocarcinoma, and high nuclear expression of WTAP was associated with a poor prognosis in pancreatic cancer patients." (PMID 34330301, 2021). "Overexpression of WTAP promoted migration, invasion, and gemcitabine resistance in pancreatic cancer cells." (PMID 36139062, 2022). "LncRNA DUXAP8 can regulate the Fak signaling pathway through miR-448/WTAP axis to promote migration and invasion of pancreatic cancer cells." (PMID 36139062, 2022). "In pancreatic cancer, WT1-associated protein (WTAP) promotes chemoresistance to gemcitabine by binding to FAK mRNA and increasing FAK expression and activity." (PMID 32514188, 2020). "In addition, in pancreatic cancer, WTAP is an independent prognostic factor for the prognosis of this tumor, and it was found that the prognosis was often poor in patients with high WTAP expression." (PMID 35733918, 2022). "Further studies have shown that WTAP promotes metastasis and chemoresistance to gemcitabine via stabilizing Fak mRNA, and a specific FAK inhibitor, GSK2256098, could restore WTAP-mediated chemoresistance and metastasis in pancreatic cancer." (PMID 34239358, 2021). "Notably, real-time PCR revealed that METTL3, METTL14, and WTAP were upregulated in pancreatic cancer tissues compared with adjacent, healthy tissues." (PMID 32843065, 2020). "In pancreatic cancer, overexpression of pseudogene Wilms tumor 1-associated protein pseudogene 1 (WTAPP1) enhances the recruitment of more translation initiation factor–eukaryotic translation initiation factor 3 (EIF3) complex (EIF3A to EIF3M) by EIF3B and promotes WTAP translation." (PMID 36139062, 2022). "To elucidate the molecular mechanisms responsible for elevated m6A levels in pancreatic cancer, we assessed the expression of the most important m6A regulatory factors (METTL3, METTL14, and WTAP, which form a complex) in the paired cancer and adjacent tissue samples." (PMID 32843065, 2020). "After treated with gemcitabine, only METTL14 was significantly increased in all six pancreatic cancer cell lines, but not METTL3, WTAP, VIRMA, FTO or ALKBH5." (PMID 34458141, 2021).
colon cancer (12 papers, 2020 to 2025). "In the context of colon cancer, targeting and degrading Wilms’ tumor 1-associating protein (WTAP) with carbonic anhydrase IV successfully restored free WT1 proteins capable of inhibiting the Wnt/β-catenin pathway, demonstrating the potential benefits of WTAP-targeting therapies." (PMID 38173713, 2023). "Additionally, WTAP upregulation in colon cancer downregulates FLNA expression through m6A modification at the 3'UTR region." (PMID 41367384, 2025). "In addition, WTAP was essential for the tumor-suppressor function of carbonic anhydrase 4 (CA4) in colon cancer." (PMID 36171885, 2022). "We suggest that WTAP expression is upregulated in CRC, highly expressed in left colon cancer and negatively correlated with tumor differentiation." (PMID 35143566, 2022). "CA4 is a tumour suppressor gene for colon cancer that inhibits the Wnt pathway by attenuating WTAP–WT1–TBL1 axis, among which WTAP is degraded because CA4 is stimulating its polyubiquitination." (PMID 32998774, 2020). "Furthermore, WTAP interacts with carbonic anhydrase IV (CA4) to induce WTAP protein degradation through polyubiquitination, which may inhibit colon cancer development by suppressing the Wnt signaling pathway." (PMID 40986143, 2025).
colorectal cancer (12 papers, 2021 to 2025). A primary or metastatic malignant neoplasm that affects the colon or rectum. "Few reports exist regarding the expression and function of Wilms’ tumor 1-associated protein (WTAP) in colorectal cancer (CRC), and the evidence is controversial." (PMID 35143566, 2022). "In colorectal cancer, studies have pointed out WTAP is also oncogenic and can promote the progression of colorectal cancer through the WTAP/WT1/TBL1 axis in the canonical Wnt signaling pathway." (PMID 35614935, 2022). "For example, it was revealed that a poor prognosis of colorectal cancers is associated with a high level of m6A RNA, and in these cells, there is an overexpression of METTL3, METTL16, and WTAP regulatory proteins." (PMID 34357041, 2021). "For instance, in colorectal cancer, the increased cell death induced by cysteine desulfurase (NFS1) or Wilms tumor 1-associating protein (WTAP) depletion under oxaliplatin treatment cannot be completely reversed by any of the inhibitors of apoptosis, pyroptosis and necroptosis alone." (PMID 40721869, 2025). "Besides, ALKBH5, FTO, METTL3, METTL14, METTL16 and WTAP were detected in a section of colorectal cancer tissue." (PMID 39039912, 2024). "Another group also suggested the higher expression of WTAP protein in colorectal cancer." (PMID 35614935, 2022). "Interestingly, WTAP overexpression in colorectal cancer enhances malignant phenotypes through the upregulation of cell proliferation, migratory capacity, invasive potential, and tumor angiogenesis, thereby establishing WTAP as a promising diagnostic/prognostic biomarker." (PMID 40986143, 2025). "Mechanistically, WTAP promotes VEGFA expression via a YTHDC1-dependent RNA splicing mechanism and activates the MAPK signaling cascade, which synergistically drives tumor angiogenesis and metastatic progression, underscoring its critical role in colorectal cancer oncogenesis." (PMID 40986143, 2025).
diffuse large B-cell lymphoma (10 papers, 2018 to 2025). "High expressions of piR-30473 support the aggressive phenotype of diffuse large B-cell lymphoma, exerting its oncogenic role through a mechanism involving the upregulation of Wilms Tumor-1 Associated Protein (WTAP), an m6A mRNA methylase, that enhances the global m6A level." (PMID 37568728, 2023). "For example, piRNA-30473 has been shown to downregulate Wilms’ tumor 1-associating protein (WTAP) expression via TGS, thereby regulating hexokinase 2 to promote the progression of diffuse large B cell lymphoma." (PMID 39827178, 2025). "Huiying Han suggested that piRNA-30473 contributes to tumorigenesis and poor prognosis in diffuse large B-cell lymphoma by regulating m6A RNA methylation through WTAP, thereby triggering downstream signaling cascades." (PMID 38182573, 2024). "Han’s study presents the fact that piRNA-30473 plays a role in diffuse large B-cell lymphoma (DLBCL) by regulating WTAP." (PMID 36882835, 2023). "PiRNA-30473 in diffuse large B-cell lymphoma (DLBCL) reduces WTAP mRNA decline and enhances WTAP mRNA stability by binding to the 3′UTR of WTAP." (PMID 36139062, 2022). "The function of WTAP in diffuse large B-cell lymphoma (DLBCL), however, remains unclear." (PMID 30143009, 2018). "Diffuse large B-cell lymphoma (DLBC), GBM, Thymoma (THYM) showed significantly higher expression of WTAP compared to normal tissues, while KICH showed the opposite trend." (PMID 36171885, 2022).
Sepsis (8 papers, 2020 to 2025). Sepsis is defined as life-threatening organ dysfunction caused by a dysregulated host response to infection. "Through analyses of clinical data and mouse disease models, we clearly found that high expression of WTAP is associated with inflammatory diseases, such as sepsis, SLE, asthma, RA, psoriasis, and IBD." (PMID 39007267, 2024). "The abundance of the WTAP mRNA was higher in the PBMCs from patients with sepsis than in those from healthy individuals." (PMID 39007267, 2024). "IGFBP1, IGFBP2, IGF2BP1, and WTAP were highly expressed in advanced sepsis patients, and the remaining 17 regulators were poorly expressed." (PMID 37330481, 2023). "Therefore, it is plausible that downregulation of METTL3 and WTAP may modulate aortic damage during sepsis." (PMID 34507301, 2021). "We observed substantial heterogeneity in the expression of demethylases (ALKBH5, FTO) and methyltransferase complex components (WTAP, METTL3, METTL14), suggesting their potential involvement in the epigenetic regulation of immune function during sepsis." (PMID 40625751, 2025). "We further investigated the potential role and clinical relevance of upregulated WTAP in the progression of inflammatory diseases, and revealed that both WTAP and IL6ST were upregulated in patients with SLE, asthma, sepsis, RA, psoriasis, and IBD." (PMID 39007267, 2024). "Trials have demonstrated a substantial correlation between m6A regulators including ALKBH5, HNRNPC, KIAA1429, WTAP, and YTHDF2 and 28-day cumulative mortality in sepsis patients." (PMID 38112620, 2023). "Using qRT-PCR, we detected that the expression of METTL3 and WTAP in the aorta was significantly downregulated during sepsis, while that of YTHDF 1, YTHDF 3, METTL14, and FTO did not change significantly." (PMID 34507301, 2021). "Clinical studies have identified genes such as WTAP and methyltransferase-like protein 16 (METTL16), which, through the modulation of m6A methylation, facilitate immune cell infiltration, accelerating the onset and progression of sepsis in both healthy individuals and late-stage sepsis patients." (PMID 39234245, 2024).
nasopharyngeal carcinoma (7 papers, 2022 to 2025). A carcinoma arising from the nasopharyngeal epithelium. "This research has identified WTAP as a possible biomarker for nasopharyngeal cancer and emphasizes the function of WTAP-mediated m6A modification in nasopharyngeal carcinoma." (PMID 38125749, 2023). "In nasopharyngeal carcinoma, KAT3A upregulates WTAP expression by mediating H3K27 acetylation, and WTAP overexpression predicts poor prognosis and promotes tumor cell growth and metastasis." (PMID 36139062, 2022).
pancreatic ductal adenocarcinoma (7 papers, 2021 to 2025). An infiltrating adenocarcinoma that arises from the epithelial cells of the pancreas. "In pancreatic ductal adenocarcinoma, WTAP is linked to CD8+ T cell infiltration and positively correlates with inflammatory gene expression profiles and various immune checkpoints." (PMID 40568348, 2025). "Moreover, METTL13/METTL14/WTAP complexes and YTHDF2 facilitate PIK3CB mRNA and protein expression levels, significantly promoting the proliferation and migration of PTEN-deficient pancreatic ductal adenocarcinoma cells." (PMID 39806412, 2025). "This study analyzed eight m6A regulators (METTL3, METTL14, WTAP, FTO, ALKBH5, and YTHDF1-3) in pancreatic ductal adenocarcinoma (PDAC) and found that only RNA m6A demethylase ALKBH5 serves as an independent favorable prognostic marker for this tumor." (PMID 34733841, 2021).
thyroid cancer (7 papers, 2021 to 2025). "Most of the key m6A regulators were positively correlated to iodide-handling genes in thyroid cancer, but IGF2BP2, HNRNPC, WTAP, and RBM15B were negatively correlated to iodide-handling genes, and the correlation between IGF2BP2 and iodide-handling gene was the strongest." (PMID 35267576, 2022).